METTL3 (methyltransferase 3, N6-adenosine-methyltransferase complex catalytic subunit)
Diseases named in the same sentence as METTL3 in open-access papers (continued):
Sharing a sentence is not in itself a finding about the gene and the disease.
tumor (continued). "The anticancer immunological response mediated by delicaflavone was reversed in tumor-bearing mice by overexpression of the N6-methyladenosine (m6A) transferase Mettl3/Mettl14." (PMID 37175435, 2023). "Overall, we designed in vivo and in vitro experimental protocols in STAD to confirm that METTL3 was a key promoter of tumor growth and metastasis." (PMID 37344779, 2023). "METTL3 has also been found to direct the m6A methylation of JAK1 mRNA in tumor-infiltrating myeloid cells (TIMs), and the m6A/YTHDF1 axis has been shown to promote JAK1 translation." (PMID 37217462, 2023). "The global view of MeRIP‐seq results of transcriptome‐wide m6A modification, demonstrates that METTL3‐dependent splicing is observed not only in tumour cells but also in non‐tumour cells." (PMID 37850412, 2023). "Collectively, these findings indicated that METTL3 was a writer for C1qA methylation that inhibited the activity of the complement system and thus promoted tumor cell proliferation both in vitro and in vivo." (PMID 37907575, 2023). "Among these writers, METTL3 mediates a methylation process that is involved in transcriptional regulation, protein, phosphorylation and tumor angiogenesis in tumor tissues." (PMID 38053093, 2023). "Specific METTL3 knockout in macrophages increases M1- and M2-like TAMs and promotes Treg enrichment into tumours, establishing an immune-suppressive TIME and limiting the efficacy of PD-1 blockade in melanoma." (PMID 36859310, 2023). "The expression of METTL3 plays a pivotal role in the anti-tumor immunity of NK cells, which are core immune cells responsible for cytotoxic effects." (PMID 38187373, 2023). "SUMO1-mediated SUMOylation of METTL3 promotes tumor progression by regulating Snail mRNA homeostasis in an m6A methyltransferase activity-dependent manner in HCC." (PMID 37391814, 2023). "Meanwhile, H3K18la promotes METTL3-mediated m6A modification to enhance the immunosuppressive effect of tumor-infiltrating myeloid cells." (PMID 37684641, 2023). "Growing evidence in recent years has demonstrated that METTL3, an m6A methyltransferase that functions as both an oncogene and a tumor suppressor gene, plays an important role in various cancers development." (PMID 38012763, 2023). "Collectively, our study results indicate that USP13 promotes glycolysis and tumor progression in OS by stabilizing METTL3, thereby stabilizing ATG5 mRNA and facilitating autophagy in OS." (PMID 37151889, 2023). "Growing evidence indicates that N6-methyladenosine (m6A) is the most common RNA modification in eukaryotic cells and that methyltransferase-like 3 (METTL3) participates in tumour progression in several cancer types." (PMID 36765397, 2023). "Mettl3 affects various biological behaviors of tumor cells by regulating m6A methylation, such as cell proliferation, apoptosis, invasion, and metastasis." (PMID 37007040, 2023). "Inhibition of METTL3 expression decreases tumor cell angiogenesis, which inhibits the distant metastasis of GC and delays cancer progression." (PMID 37443100, 2023). "Increasing evidence suggests that METTL3 affects the malignant behaviors of tumor cells and GC prognosis." (PMID 37443100, 2023). "This study is dedicated to exploring the regulation of METTL3 and the specific mechanisms by which METTL3 affects tumor biological behavior, thus providing some reference for clinical development and application of drugs targeting METTL3." (PMID 37996892, 2023). "In NSCLC, miR‐33a was validated to be decreased and attenuated aggressive tumour phenotype via disturbing METTL3 expression." (PMID 36162823, 2023). "While these investigations weren’t specifically carried out in a tumor setting, they offer valuable insights into how METTL3/14 regulates B cells." (PMID 38187373, 2023).
tumor (continued). "The administration of anti-PD-1 antibody to mice with treated with METTL3-knockdown M2 macrophages led to a more significant delay in tumor growth compared to those receiving anti-PD-1 antibody with control M2 macrophages." (PMID 37402945, 2023). "Some studies have shown that blocking METTL3 can enhance the chemotherapeutic response and reduce stem cell frequency and tumor size both in vitro and in vivo." (PMID 37427112, 2023). "Remarkably, METTL3 plus anti-PD-1 therapy demonstrated synergistic inhibition of tumor growth as compared to control (p = 0.008), sgMETTL3 (p = 0.032), and anti-PD-1 (p = 0.008) groups, achieving >90% reduction in tumor volume and weight." (PMID 37586322, 2023). "Among these, Cybb indicated significant up-regulation in granulocytes isolated from periteoneal lavage of Mettl3-cKO mice with ID8 tumor-bearing compared with WT mice." (PMID 37932814, 2023). "Of note, METTL3 remodels neutrophil infiltration in the tumor microenvironment by regulating the m6A/c-Rel/IL-8 network, thereby inhibiting PTC progression." (PMID 35864970, 2022). "Taken all together, METTL3 acetylation triggered by ASP/NAM treatment elicited a suppressive effect on invasiveness of tumor cells via impacting on both pro-metastasis and anti-metastasis pathways in an m6A-dependent manner." (PMID 36289222, 2022). "This study’s findings that higher METTL3 mRNA expression in primary tumour samples compared to normal prostate tissue, is consistent with recently published studies." (PMID 36291932, 2022). "Functionally, we verified that METTL3 promoted tumor cell proliferation and angiogenesis through a series of phenotypic experiments." (PMID 35574388, 2022). "This study further demonstrated that METTL3 plays a tumor-suppressive role in the proliferation, migration and invasion of CRC cells through the p38/ERK pathway." (PMID 35155557, 2022). "Nevertheless, it was reported that METTL3-mediated m6A RNA methylation promotes the anti-tumor immunity of natural killer cells." (PMID 35813476, 2022). "METTL3 dysregulation has already been widely reported in a wide range of tumor types, such as lung cancer, colorectal cancer and breast cancer." (PMID 35574315, 2022). "In mice, they observed that depletion of Mettl3 enhanced NK-cell responsiveness to IL-15 and promoted tumour progression and metastasis by targeting SHP-2." (PMID 36407103, 2022). "Further validation showed that circMETTL3 served as a sponge for miR-34c-3p and exerted tumor-promoting functions by upregulating the expression of METTL3." (PMID 36035182, 2022). "In contrast, METTL3 regulates tumor growth by cooperating with YTHDF2 to modify tumor-associated neutrophils (TANs) infiltration and performs a key tumor suppressor role in papillary thyroid carcinoma." (PMID 36386128, 2022). "Their findings demonstrated that lactate accumulated in the tumor microenvironment effectively increased methyltransferase-like 3 (METTL3) in TIMs via H3K18la." (PMID 36081996, 2022). "Analysis of publicly available PCa datasets confirmed that METTL3 copy number and mRNA expression is altered frequently in PCa patients, including in advanced tumour types, supporting a role for METTL3 in PCa progression." (PMID 36291932, 2022). "Following the extraction of RNA and protein from 4 pairs, it was discovered that the levels of METTL3 mRNA and protein expression in tumor tissues were higher than those in adjacent tissues." (PMID 36386128, 2022). "Further analysis demonstrated that METTL3 high status was negatively correlated with tumor immune cell infiltrations and facilitated the expression of immunosuppressive immune checkpoint molecules (i.e., PD-L1)." (PMID 35813476, 2022). "Among all HATs tested, only ectopic p300 completely blunted migration/invasion of METTL3-expressing cells, demonstrating that p300 counteracts with METTL3 in promoting tumor cell invasiveness via catalyzing its acetylation." (PMID 36289222, 2022).
tumor (continued). "Another study demonstrated a link between the gut microbiome and cellular m6A levels by showing that butyrate, a bacterial short-chain fatty acid, decreases METTL3 levels in vitro, thus suppressing tumor cell growth." (PMID 36008936, 2022). "As an important epitranscriptome modulator, methyltransferase-like 3 (METTL3) has been reported to promote tumor angiogenesis and glycolysis by regulating HDGF m6A modification in GC." (PMID 35114989, 2022). "The results showed that the expression of the m6A “writer” METTL3 was decreased in tumor-infiltrated NK cells, and the protein expression level of METTL3 was positively correlated with the effector molecules in NK cells." (PMID 36505499, 2022). "It showed that knockdown of METTL3 significantly restrained tumor growth, as reflected by tumor volume and weight." (PMID 35287752, 2022). "On the one hand, METTL3 affects m6A levels of oncogenes or tumor suppressors, thereby regulating their expression to promote tumor progression." (PMID 35331234, 2022). "METTL3 enhances the stability of PD-L1 mRNA, promotes the expression of PD-L1 and induces tumor immunosuppression by relying on m6A modification." (PMID 35784761, 2022). "Increasing evidence is depicting the roles of METTL3 in the tumor immune microenvironment and METTL3 as a potential therapeutic target for tumor immunotherapy." (PMID 36008936, 2022). "Tremendous studies have shown that METTL3 promotes tumor growth, metastasis, and drug resistance in human cancers." (PMID 36167542, 2022). "B-NDG and BALB/c mice were used to construct xenograft tumor models to verify the phenotypes upon METTL3 and IGF2BP3 silencing." (PMID 35197058, 2022). "Our previous study found that METTL3 acts as a tumor suppressor in PTC by influencing the m6A modification of c-Rel and RelA mRNAs, thereby altering tumor-associated neutrophils (TANs) infiltration to regulate tumor growth." (PMID 36522683, 2022). "The expression level of METTL3 was significantly higher in tumor tissues compared to that in adjacent normal tissues according to the analysis of all patients in the GEO87410 dataset." (PMID 36614956, 2022). "We also found that high expression of METTL3 was associated with advanced TNM stage and pT stage, pN stage, tumor size >5 cm and vascular invasion respectively." (PMID 36347025, 2022). "Samples from a cohort of 145 patients found that high expression of METTL3 correlated with longer patient survival, indicating a tumor suppressive role for METTL3 in RCC." (PMID 36008936, 2022). "The results suggested that silencing METTL3 eliminated the progression of xenograft tumors and increased the abundance of infiltrating immune cell types in the tumor microenvironment." (PMID 35197058, 2022). "In this study, we found that the expression of m6A regulators was up-regulated in HCC tissues, and the up-regulated expression of YTHDF1/2, YTHDC1, RBM15 and METTL3 was significantly correlated with the tumour stage of HCC patients." (PMID 36434140, 2022). "Mechanistically, exosomal circLPAR1 was internalized by CRC cells, and it suppressed tumor growth, likely because exosomal circLPAR1 directly bound with eIF3h specifically suppressed the METTL3-eIF3h interaction, decreasing the translation of oncogene BRD4." (PMID 35164758, 2022). "As confirmed by qPCR and western blot, CDC25B expression was downregulated upon knockdown of METTL3 in tumor tissues." (PMID 35287752, 2022). "METTL3 has been reported to have both oncogenic and tumour suppressor roles in a number of cancer types." (PMID 36733939, 2022). "Recent evidence has found that METTL3, depending on its methyltransferase activity, serves as an oncogene or tumor suppressor in different cancers." (PMID 34996469, 2022). "METTL3 is a key member of the m6A methyltransferase complex, and is also a pivotal oncogene for tumor development in multiple malignancies." (PMID 35467477, 2022).
tumor (continued). "Taken together, all these data indicate that NR4A1 functions as tumor suppressor and dramatically abrogates the malignant phenotype induced by METTL3 in CC cells." (PMID 36566195, 2022). "Because canonical full-length METTL3-A regulates the carcinogenesis, tumor progression, and drug resistance of HCC, we carefully detected the levels of METTL3 splicing variants in normal human liver, HCC tumor tissues, and HepG2 cells using RT-qPCR." (PMID 35456475, 2022). "YTHDF1 and METTL3 expression at protein levels were all upregulated in five tumor tissues compared to their paired normal tissues." (PMID 36008805, 2022). "METTL3 is upregulated in HCC patient tumor tissues, leading to increased mRNA m6A modification and enhanced progression of HCC." (PMID 35456475, 2022). "This study chose to focus on the role of METTL3 due to elevated m6A levels in tumor vs normal patient total RNA samples although this was measured in only five patient samples." (PMID 36008936, 2022). "Methyltransferase 3 (METTL3), among the first identified m6A methyltransferases, is highly expressed in a variety of tumor tissues, where it promotes mRNA translation and regulates tumor cell proliferation by regulation of the methylation of target genes." (PMID 36064747, 2022). "Our results demonstrated that METTL3 was highly expressed in OS, and correlated with the tumor size, clinical stage, and distant metastasis of OS patients." (PMID 35396379, 2022). "Further, in vitro and in vivo studies indicated that METTL3 promotes HNSCC tumor growth, as well as cell proliferation, migration, invasion, cell cycle progression, and angiogenesis." (PMID 35287752, 2022). "Subsequently, METTL3 suppression in cell-derived xenografts exhibited a significant inhibitory effect in tumor growth, which further indicated the oncogenic role of METTL3 in LUAD tumorigenesis." (PMID 34996469, 2022). "For example, METTL3 deletion in macrophages can promote tumor growth, metastasis, and drug resistance by increasing M1- and M2-TAM and Treg infiltration in tumors and reshaping the tumor microenvironment." (PMID 35331234, 2022). "As epitranscriptomic writers for m6A methylation, the m6A methylases METTL3 is involved in various stages of multiple hematoma and solid malignancies, including tumor stemness, immune microenvironment, drug resistance, metastasis and recurrence." (PMID 35164788, 2022). "Despite the discrepancy in METTL3 expression levels in different hematological malignancies, METTL3 is upregulated in most tumor tissues and cell lines and is involved in disease progression and the maintenance of a cancer cell undifferentiated state." (PMID 35574332, 2022). "The results from the knockdown and overexpression models led us to conclude that METTL3 played a critical role in promoting tumor growth in vivo." (PMID 35637959, 2022). "Previous studies showed that the expression of m6A writers (METTL3, RBM15, WTAP), eraser (FTO, ALKBH5) and reader (YTHDF3, YTHDC2) was associated with pathological stage, tumor stage, andprognosis of patients with GC." (PMID 35977935, 2022). "Our results exhibited that METTL3 expression was correlated with tumor size, clinical stage, and distance metastasis (p < 0.05), and higher METTL3 expression indicated worse overall survival rate (p < 0.05)." (PMID 35396379, 2022). "Particularly, m6A writers showed high up-regulated expression in tumor samples, such as METTL3, RBM15, RBM15B and WTAP." (PMID 35847857, 2022). "Increased expression of METTL3 in tumor infiltrating myeloid cells (TIMs) correlates with the poor prognosis of colon cancer patients." (PMID 36008936, 2022). "In this review, we discuss the multifaceted roles of METTL3 in regulating specific molecular signaling pathways in different types of cancers and the recent progress on how METTL3 impacts the tumor immune microenvironment." (PMID 36008936, 2022).
tumor (continued). "Given that m6A writers are important for cancer progression, usually as a tumor promoter during tumor progression, this study explored the expression of m6A writers, including METTL3, METTL14, and WTAP, in tumor and adjacent normal tissues." (PMID 35778697, 2022). "In the present study, rescue experiments revealed that silencing STEAP2 partially rescued the tumor-suppressive phenotype induced by METTL3 overexpression." (PMID 35436987, 2022). "Our biological function studies illustrated that knocking down METTL3 considerably reduced cell proliferation, migration, and tumor growth of arecoline-transformed OSCC." (PMID 36429032, 2022). "On the contrary, there is much evidence to prove the overexpression of METTL3 in tumor tissues, while studies targeting METTL3 have shown that it can effectively inhibit tumor growth, proliferation, and metastasis." (PMID 35707365, 2022). "The m6A reader protein YTHDF2-dependent RNA degradation pathway mediates the degradation of SOCS2 mRNAs, suggesting that METTL3 represses the expression and stability of critical tumor suppressor genes at the posttranscriptional level." (PMID 36446846, 2022). "Immunohistochemistry staining (IHC) also showed a significantly increased expression of METTL3 in CC tissues compared to adjacent non-tumor tissues." (PMID 36566195, 2022). "Validated by RT–qPCR and Western blotting, we found that METTL3-D, one of the splice variants expressing a truncated METTL3 protein, exhibits higher levels than METTL3-A in normal human livers but lower levels than METTL3-A in HCC tumor tissues and cell lines." (PMID 35456475, 2022). "The significant associations between METTL3 expression and immune factors in the TME suggest that METTL3 plays important roles in the tumor immune microenvironment and that therapeutic approaches can be developed to target METTL3." (PMID 36614956, 2022). "Dysregulated METTL3 signaling has been shown to potentiate cancer cell invasion and tumor metastasis." (PMID 36289222, 2022). "In this study, by integrative trans-omic analyses of m6A regulators in HNSC and CESC, we identified the key m6A regulator METTL3 in tumor HPV status, HPV expression, suppressive TIME, and suppressive immune checkpoint molecules in HPV-associated cancers." (PMID 35813476, 2022). "Third, the specific mechanisms by which METTL3 influences the tumor immune microenvironment should be further evaluated." (PMID 36614956, 2022). "Using mouse models, they also showed that deleting METTL3 reduced NK cell hyporesponsiveness to IL-15, promoted tumor progression and metastasis by targeting SH2 domain-containing protein tyrosine phosphatase-2 (SHP-2)." (PMID 35296338, 2022). "Our findings affect the m6A-related gene YTHDF1 and dendritic cells in immunity, and METTL3 enhanced the response to anti-PD-1 treatment, which suggests that these lncRNAs enhance the effect of tumor immunotherapy by regulating m6A-related target genes." (PMID 36168326, 2022). "METTL3 was shown to be much more highly expressed in CRC tumor tissues, while METTL14 was much more expressed in normal CRC tissues." (PMID 36230970, 2022). "This study found that METTL3 expression is significantly negatively correlated with the tumor size and metastasis but positively correlated with patient prognosis; that is, a higher METTL3 expression in tumor is related to a better prognosis." (PMID 35155557, 2022). "In CRC, the lactate accumulation in the tumor microenvironment can induce the METTL3 expression in tumor-infiltrating myeloid cells (TIMs) via histone lactylation." (PMID 36319992, 2022). "As the sole catalytic subunit in the methyltransferase complex, METTL3 is involved in different aspects of tumor progression, such as cell proliferation, invasion, migration, metastasis, tumor environment, cancer stem cells, and drug resistance." (PMID 35331234, 2022).